IRGM (immunity related GTPase M)
Description:
Immunity-related GTPase that plays important roles in innate immunity and inflammatory response. Acts as a dynamin-like protein that binds to intracellular membranes and promotes remodeling and trafficking of those membranes (By similarity). Required for clearance of acute protozoan and bacterial infections by interacting with autophagy and lysosome regulatory proteins, thereby promoting the fusion of phagosomes with lysosomes for efficient degradation of cargo including microbes. Regulates selective autophagy, including xenophagy and mitophagy, both directly and indirectly. Directly regulates autophagy by acting as a molecular adapter that promotes the coassembly of the core autophagy machinery to mediate antimicrobial defense: IRGM (1) activates AMPK, which in turn phosphorylates ULK1 and BECN1 to induce autophagy, (2) promotes the coassembly of ULK1 and BECN1, enhancing BECN1-interacting partners and (3) influences the composition of the BECN1 complex, by competing with the negative regulators BCL2 and RUBCN, to trigger autophagy. Also activates autophagy by promoting recruitment of STX17 to autophagosomes. In collaboration with ATG8 proteins, regulate lysosomal biogenesis, a fundamental process for any autophagic pathway, by promoting TFEB dephosphorylation. Also modulates autophagy by assisting with autophagosome formation and preventing lysosomal deacidification (By similarity). While activating autophagy, acts as a key negative regulator of the inflammatory and interferon responses both by (1) promoting mitophagy and (2) mediating autophagy-dependent degradation of effectors of the inflammatory response. Promotes degradation of damaged and IFNG/IFN-gamma-stressed mitochondria via mitophagy, preventing cytosolic release of ligands that activate inflammation. Acts as a suppressor of inflammation by promoting recruitment of inflammation effectors, such as CGAS, RIGI/RIG-I and NLRP3, to autophagosome membranes, leading to their SQSTM1/p62-dependent autophagic degradation. Also directly inhibits assembly of the NLRP3 inflammasome by preventing the association between NLRP3 and PYCARD. Acts as a negative regulator of antiviral innate immune response by suppressing the RIPK2-dependent pro-inflammatory response: mediates recruitment of RIPosomes, composed of RIPK2 and NOD1 or NOD2, to autophagosome membranes, promoting their SQSTM1/p62-dependent autophagic degradation. [Isoform IRGMd]: Acts as a positive regulator of mitophagy in response to intracellular mycobacteria infection: specifically binds cardiolipin, leading to its translocation to mitochondria, where it promotes affected mitochondrial fission and mitophagy. (Microbial infection) Following infection by hepatitis C virus (HCV), promotes HCV-triggered membrane remodeling, leading to autophagy and Golgi fragmentation, a step required for HCV replication.
Synonyms: LRG-47; IFI1; IRGM1; LRG47; IBD19
Tractability: Antibody: UniProt places it where antibodies can reach, with medium confidence; its Gene Ontology location is reachable by antibodies, with medium confidence. PROTAC: UniProt records ubiquitination sites on it.
Target class: Enzyme; Hydrolase
Gene: Protein-coding gene on chromosome 5 (150,846,521 to 150,900,736, forward strand). Ensembl gene ENSG00000237693.
Subcellular location: Golgi apparatus membrane; Cell membrane; Cytoplasmic vesicle, phagosome membrane; Cytoplasmic vesicle, autophagosome membrane; Lysosome membrane; Late endosome membrane; Mitochondrion membrane; Cell projection, phagocytic cup; Mitochondrion (Isoform IRGMd)
Gene Ontology:
Molecular function: BH3 domain binding; CARD domain binding; G protein activity; GTPase activity; protein binding; protein kinase binding; protein serine/threonine kinase activator activity; protein-macromolecule adaptor activity; GTP binding
Biological process: autophagosome assembly; CAMKK-AMPK signaling cascade; cellular response to lipopolysaccharide; cellular response to virus; defense response to bacterium; defense response to Gram-negative bacterium; innate immune response; negative regulation of canonical NF-kappaB signal transduction; negative regulation of cGAS/STING signaling pathway; negative regulation of defense response to virus; negative regulation of inflammatory response; negative regulation of NLRP3 inflammasome complex assembly; negative regulation of type I interferon production; nucleotide-binding oligomerization domain containing 2 signaling pathway; positive regulation of autophagosome maturation; positive regulation of autophagy; positive regulation of lysosome organization; positive regulation of mitophagy; positive regulation of peptidyl-serine phosphorylation; positive regulation of peptidyl-threonine phosphorylation; positive regulation of protein phosphorylation; positive regulation of protein serine/threonine kinase activity; positive regulation of type II interferon-mediated signaling pathway; positive regulation of xenophagy; protein destabilization; and 10 more
Cellular component: autophagosome membrane; cytosol; Golgi apparatus; Golgi membrane; mitochondrion; endoplasmic reticulum membrane; late endosome membrane; lysosomal membrane; mitochondrial membrane; plasma membrane; membrane; phagocytic cup; phagocytic vesicle membrane
Genetic constraint (gnomAD): Loss-of-function variants: 0 observed, 0.74 expected, observed/expected ratio (o/e) 0, 90% interval 0 to 1.79. That is too few expected variants to judge how well the gene tolerates losing a copy. Missense variants: 286 observed, 227.94 expected, observed/expected ratio (o/e) 1.25, 90% interval 1.14 to 1.38. Synonymous variants: 96 observed, 83.21 expected, observed/expected ratio (o/e) 1.15, 90% interval 0.98 to 1.37.
Homologues: Orthologues: chimpanzee IRGM (96% identical), rat Irgm (57% identical), mouse Irgm1 (55% identical), mouse Irgm2 (54% identical), rat Igtp (53% identical), mouse Igtp (52% identical), guinea pig IFGGD1 (49% identical), zebrafish si:ch73-171o20.1 (37% identical), zebrafish irgf1 (35% identical), zebrafish irgf2 (35% identical), zebrafish irgf3 (34% identical). Paralogues in human: IRGC (33% identical).
Diseases named in the same sentence as IRGM in open-access papers:
IRGM is named in the same sentence as 77 diseases in open-access papers, as found by Europe PMC text mining. Sharing a sentence is not in itself a finding about the gene and the disease. The quoted sentences say what the papers report.
Crohn disease (55 papers, 2009 to 2026). A gastrointestinal disorder characterized by chronic inflammation involving all layers of the intestinal wall, noncaseating granulomas affecting the intestinal wall and regional lymph nodes, and transmural fibrosis. "As research progresses, more and more autophagy-related Crohn's disease susceptibility genes have been identified, such as IRGM, ULK1, LRRK2, TLR4, etc.." (PMID 39883213, 2024). "The minor allele of rs13361189 (−4299T>C), a single nucleotide polymorphism in the IRGM promoter, has been associated with several diseases, including Crohn’s disease and tuberculosis." (PMID 37558924, 2023). "Genetic mutations in the Immunity‐related GTPase M (IRGM) gene or promoter are suggested to increase susceptibility to several inflammatory and infectious diseases including Crohn's disease, tuberculosis, sepsis, and ankylosing spondylitis." (PMID 36221902, 2022). "In genome-wide association studies, mutations in IRGM were strongly associated with susceptibility to Crohn’s disease and tuberculosis." (PMID 36578501, 2022). "The human IRGM gene has been strongly associated with Crohn’s disease and other inflammatory diseases through Genome-Wide Association studies." (PMID 35039539, 2022). "The family of immunity-related GTPases, including homologs of human Crohn’s disease susceptibility gene IRGM, were downregulated." (PMID 34202278, 2021). "The SNPs and deletion polymorphisms in promoter and exonic regions of IRGM have been shown to be strongly associated with susceptibility to Crohn's disease and other autoimmune diseases." (PMID 32715615, 2020). "Significant correlation between Crohn's disease (CD) and the C allele of rs13361189 (OR= 1.33) of the IRGM gene was noted in an Indian Population." (PMID 29992164, 2018). "A recent study revealed that a synonymous SNP in IRGM alters a binding site for miR-196 and caused deregulation of IRGM-dependent xenophagy in Crohn’s disease." (PMID 26437399, 2015). "We also report, for the first time, an association of rs 9637876 in the IRGM gene with Crohn's disease." (PMID 25191865, 2014). "The autophagy-stimulating IRGM gene has been recognised as an independent major Crohn's disease susceptibility locus in several studies." (PMID 25191865, 2014). "Single nucleotide polymorphisms (SNPs) in the IRGM gene have been reported to be associated with Crohn's disease." (PMID 25191865, 2014). "Associations between SNPs in the promoter region of IRGM and reduced IRGM gene expression have been confirmed in lymphocytes from Crohn's disease patients." (PMID 25191865, 2014). "The possible involvement of IRGM polymorphism in the development of Crohn’s disease, an inflammatory bowel disease, has been reported." (PMID 24626347, 2014). "Investigation showed that variations of IRGM gene are associated with an increased risk of several diseases such as Crohn's disease and tuberculosis." (PMID 23049477, 2012). "IRGM is a member of the antimicrobial immunity-related GTPase family (also called p47 GTPases) family that can induce autophagy and was first linked to Crohn’s disease by GWAS." (PMID 21994779, 2011). "Variants in the gene encoding immunity-related p47 guanosine triphosphatase (IRGM) were associated with Crohn's disease in a recent GWAS." (PMID 22190939, 2011). "One member of this gene family in humans, IRGM, has been recently implicated as a risk factor for Crohn's disease." (PMID 19266026, 2009). "The IRG gene family plays an important role in defense against intracellular bacteria, and genome-wide association studies have implicated structural variants of the single-copy human IRGM locus as a risk factor for Crohn's disease." (PMID 19266026, 2009). "The blood monocyte-derived macrophages (BMDMs) from patients with Crohn disease exhibit increased AIEC replication compared to those from healthy individuals, and this defect in AIEC clearance is linked to the Crohn disease-associated variants in the autophagy-related genes IRGM and ULK1." (PMID 40910070, 2025).
Crohn disease (continued). "Polymorphisms in the IRGM gene that are associated with Crohn's disease risk could alter expression levels and disrupt cellular functions crucial for initiating and sustaining autophagy against resilient intracellular bacteria." (PMID 39883213, 2024). "There were 455 citations for “Colorectal Carcinoma: A General Overview and Future Perspectives in Colorectal Cancer”, followed by “A synonymous variant in IRGM alters a binding site for miR-196 and causes deregulation of IRGM-dependent xenophagy in Crohn’s disease”, with 403 citations." (PMID 36110534, 2022). "Further, our study also suggests that inhibition of RIPK2 could be a good therapeutic strategy for suppression of gut inflammation associated with IRGM depletion, a risk factor in the progression of Crohn's disease." (PMID 36221902, 2022). "IRGM/Irgm1 is involved in autophagy and has been implicated in Crohn’s disease." (PMID 32703253, 2020). "The first GWAS finding that was explained by polymorphic miRNA targeting was the synonymous SNP (c.313C > T) in the 3′UTR of IRGM (immunity-related GTPase family M protein).This SNP decreases the binding of mir-196 and is associated with the risk of Crohn's disease." (PMID 25884492, 2015). "In particular, IRGM proteins help trigger autophagy in cells infected with mycobacteria, and several polymorphisms in or near IRGM have been associated with an increased risk of developing Crohn’s disease." (PMID 26439498, 2015). "Genome-wide association studies (GWAS) have revealed small nucleotide polymorphisms (SNPs) in autophagy genes such as ATG16lL and in additional genes now known to influence autophagic processing (i.e., NOD2 and IRGM) associated with susceptibility to Crohn's disease." (PMID 22190939, 2011). "Interestingly, small nucleotide polymorphisms occurring in the IRGM-1 gene, as implicated in Crohn's disease, were recently also linked to increased susceptibility to M. tuberculosis infection." (PMID 22190939, 2011). "We also used CUBAP to identify a significant bias toward decreased CTG pairing in the immunity related GTPase M (IRGM) gene in East Asian and African populations, which may contribute to the decreased association of rs10065172 with Crohn's disease in those populations." (PMID 33045750, 2020). "Similarly, Deretic and colleagues reported that immunity-related GTPase family M protein (IRGM)—which is a risk factor in Crohn’s disease—can assemble the core auto-phagy machinery and link it to innate immunity receptors, collectively promoting antimicrobial autophagy." (PMID 26390974, 2015). "Interestingly, autophagy genes ATG16L1 and IRGM appear to be more specific for Crohn's disease and IRGM risk alleles may predispose even more specifically to the ileal form of Crohn's disease." (PMID 21188215, 2010). "IBDs, including UC and Crohn’s disease, are characterized by autophagy pathways, with autophagy-related genes (ATG16L1, immunity-related GTPase M) identified as the susceptibility loci." (PMID 41487454, 2026). "Crohn disease-associated variants in ATG16L1, IRGM, and NOD2 are linked with a defect in autophagy-mediated AIEC clearance accompanied by enhanced pro-inflammatory cytokine production in epithelial cells and macrophages." (PMID 40910070, 2025). "Among them, ATG16L1, NOD2, IRGM, and LRRK2 are autophagy-associated genes, which highlights the key role of autophagy in genetic susceptibility of Crohn's disease." (PMID 39883213, 2024). "Our results lay a groundwork for future studies into understanding the influence of IRGM/Irgm1 regulation of T cell function and survival in Crohn’s Disease (CD)." (PMID 35039539, 2022). "IRGM in humans is an ortholog to this family, with links to Crohn’s disease, inflammatory disorders, and non-alcoholic fatty liver disease." (PMID 34202278, 2021). "Despite being identified in 2007 as a Crohn’s disease susceptibility gene, the role of IRGM–and the murine orthologue, Irgm1 –in intestinal immunity has remained unclear." (PMID 32453761, 2020).
Crohn disease (continued). "For example, the minor allele of rs10065172 reduces the binding capacity to miR-196 and therefore dysregulates the expression of IRGM in Crohn's disease." (PMID 32226509, 2020). "By suppressing inflammasome activation, IRGM/Irgm1 protects from pyroptosis and gut inflammation in a Crohn’s disease experimental mouse model." (PMID 30612879, 2019). "In Crohn’s disease, many associations with autophagy-related genes, such as ATG16L1, IRGM, NOD2, and others, have been reported." (PMID 30583538, 2018). "There are numerous genes that are involved in autophagy, including ATG16L1, NDP52, IRGM, and LRRK2 that have been found to be mutated in Crohn’s Disease patients; a number of these mutations also manifest with multiple clinical presentations." (PMID 29743550, 2018). "For example, rs10065172, a Crohn’s disease-associated SNP, lies within the 3′UTR of the IRGM (immunity-related GTPase M) gene and alters the complementary target sequence of miRNA-196." (PMID 26249223, 2016). "Polymorphisms in the genes encoding the autophagy-related proteins Atg2a, Atg4a, Atg4d, death-associated protein, immunity-related GTPase family M protein (IRGM), and ULK-1 have been found to be associated with susceptibility to Crohn’s disease." (PMID 26045969, 2015). "Regarding genes involved in autophagy, we have chosen IRGM and ATG16L1 as candidate genes, since they were associated with Crohn's disease." (PMID 25369137, 2014). "The aim of the present meta-analysis was to evaluate the correlation between a common polymorphism, rs13361189 C>T in the immunity-related GTPase M (IRGM) gene, and susceptibility to Crohn’s disease (CD)." (PMID 25009628, 2014). "Although not implicated in endometriosis thus far, IRGM is a known genetic risk factor for several autoimmune diseases, including Sjogren syndrome and Crohn's disease, raising the possibility of utility as a diagnostic marker for endometriosis." (PMID 39385609, 2024). "Genetic variations in genes encoding for autophagy-related 16-like 1 (ATG16L1), Unc-51-like autophagy-activating kinase (ULK1), immunity-related GTPase family M protein (IRGM) and nucleotide-binding oligomerization domain-containing protein 2 (NOD2) have all been associated with Crohn's disease." (PMID 33973626, 2021). "Mutations in the IRGM gene have been associated with Crohn's disease in several populations but have not been explored in Indian patients with this disease." (PMID 25191865, 2014). "Similarly, polymorphisms in the genes encoding other autophagy-related proteins, including Atg2a, Atg4a, Atg4d, Immunity-related GTPase M (IRGM), and ULK-1, have also been associated with Crohn’s disease." (PMID 23577011, 2013). "On the other hand, previously reported disease-associated CNVs were detected using this approach like, for example, well-known deletions spanning IRGM, LCE3 and ARMS2 loci, which have been respectively associated to Crohn's disease, psoriasis and age-related macular degeneration." (PMID 23844243, 2013). "Genetic studies have identified allelic variants of the autophagy genes ATG16L1 (autophagy related 16-like 1) and IRGM (immunity related GTP-ases, M) as important risk factors for Crohn's disease, an autoinflammatory disease characterized by severe chronic inflammation of the gut mucosa." (PMID 21490934, 2011). "IRGM (immunity-related GTPase M) supports autophagic degradation of NLRP3 and ASC in a p62-dependent manner and protects from gut inflammation in a mouse model of Crohn’s disease." (PMID 34206503, 2021). "Without MiR-196 regulation, IRGM is overexpressed and alters xenophagy of gut bacteria, thereby increasing the likelihood of developing Crohn's disease." (PMID 33045750, 2020). "For instance, genetic studies have demonstrated that the immunity-related GTPase family M protein (IRGM) and autophagy related 16 like 1 (Atg16L1), which are two proteins involved in autophagy pathways, are involved in the inflammatory syndrome Crohn’s disease." (PMID 32604771, 2020).
Crohn disease (continued). "In addition, IRGM1 and human IRGM (the human homolog of mouse Irgm/Lrg47) have roles in the autophagic elimination of mycobacteria and contribute genetically to Crohn’s disease and TB." (PMID 30322337, 2019). "We find that Irgm1 –the orthologue of the human Crohn’s disease resistance gene, IRGM–is required for monocyte/macrophage remodeling in response to the gram-negative enteric pathogen Citrobacter rodentium, with absence of Irgm1 leading to systemic spread of the bacterium and host mortality." (PMID 32453761, 2020).